STK16 (serine/threonine kinase 16)
Description:
Membrane-associated protein kinase that phosphorylates on serine and threonine residues. In vitro substrates include DRG1, ENO1 and EIF4EBP1. Also autophosphorylates. May be involved in secretory vesicle trafficking or intracellular signaling. May have a role in regulating stromal-epithelial interactions that occur during ductal morphogenesis in the mammary gland. May be involved in TGF-beta signaling. Able to autophosphorylate on Tyr residue; it is however unclear whether it has tyrosine-protein kinase toward other proteins.
Synonyms: MPSK; MPSK1; PKL12; TSF1; KRCT; PSK; hPSK
Tractability: Small molecule: a structure with a bound ligand is known; a high-quality ligand is known; it has a high-quality binding pocket; it belongs to a druggable protein family. Antibody: its Gene Ontology location is reachable by antibodies, with high confidence; the Human Protein Atlas places it where antibodies can reach. PROTAC: ubiquitination databases record sites on it; its protein half-life has been measured; a small molecule that binds it is known.
Target class: Protein Kinase; Other protein kinase NAK family; Other protein kinase group; Enzyme; Kinase
Chemical probes: STK16-IN-1
Gene: Protein-coding gene on chromosome 2 (219,245,455 to 219,250,339, forward strand). Ensembl gene ENSG00000115661.
Subcellular location: Cytoplasm, perinuclear region; Membrane
Subcellular location (Human Protein Atlas): Cytosol; Basal body; Nuclear bodies; Nucleoplasm; Plasma membrane; Primary cilium; Primary cilium tip
Gene Ontology:
Molecular function: protein binding; protein serine/threonine kinase activity; ATP binding; non-membrane spanning protein tyrosine kinase activity; protein kinase activity; protein serine kinase activity; protein tyrosine kinase activity; RNA polymerase II cis-regulatory region sequence-specific DNA binding
Biological process: protein autophosphorylation; cellular response to transforming growth factor beta stimulus; positive regulation of transcription by RNA polymerase II
Cellular component: cytosol; cytoplasm; Golgi apparatus; Golgi-associated vesicle; membrane; perinuclear region of cytoplasm
Genetic constraint (gnomAD): Loss-of-function variants: 28 observed, 39.16 expected, observed/expected ratio (o/e) 0.72, 90% interval 0.53 to 0.98. The upper end of that interval is the gene's LOEUF score, 0.98, which puts it in group 4 of 6, group 1 being the genes least tolerant of losing a copy. Missense variants: 349 observed, 409.06 expected, observed/expected ratio (o/e) 0.85, 90% interval 0.78 to 0.93. Synonymous variants: 134 observed, 163.03 expected, observed/expected ratio (o/e) 0.82, 90% interval 0.71 to 0.95.
Homologues: Orthologues: macaque STK16 (99% identical), chimpanzee STK16 (97% identical), rabbit STK16 (96% identical), dog STK16 (96% identical), rat Stk16 (95% identical), pig STK16 (95% identical), guinea pig STK16 (94% identical), mouse Stk16 (94% identical), tropical clawed frog stk16 (68% identical), zebrafish stk16 (64% identical), Drosophila melanogaster CG1227 (40% identical). Paralogues in human: AAK1 (32% identical), BMP2K (31% identical).
Diseases named in the same sentence as STK16 in open-access papers:
STK16 is named in the same sentence as 13 diseases in open-access papers, as found by Europe PMC text mining. Sharing a sentence is not in itself a finding about the gene and the disease. The quoted sentences say what the papers report.
lung adenocarcinoma (2 papers, 2022 to 2023). A carcinoma that arises from the lung and is characterized by the presence of malignant glandular epithelial cells. "In lung adenocarcinoma, miR-181a-5p in exosomes from M1 macrophages inhibited STK16 (Serine/threonine kinase 16) expression through ETS1 to regulate cell apoptosis." (PMID 36986884, 2023). "MiRNA-181a-5p delivered by M1-sEVs inhibit the expression of STK16 by targeting ETS1 to regulate cell viability and apoptosis in lung adenocarcinoma (LUAD), while STK16 silencing significantly reduces the mass of nodules in tumor models, thus promoting the apoptosis of LUAD cells." (PMID 35832790, 2022).
colorectal cancer (1 paper, 2024). A primary or metastatic malignant neoplasm that affects the colon or rectum. "CCK8 assays confirmed that the loss of STK16 significantly hindered colorectal cancer cell proliferation." (PMID 38622518, 2024). "However, the detailed mechanism underlying STK16’s regulation of colorectal cancer progression remained unclear." (PMID 38622518, 2024). "To evaluate its role, we initially examined STK16 expression in colorectal cancer and normal colorectal tissue using TCGA databases." (PMID 38622518, 2024). "Considering the inevitability of distant metastasis in the progression of colorectal cancer, we also examined the impact of STK16 on cell colony formation and metastatic potential." (PMID 38622518, 2024). "We demonstrated that STK16 promoted colorectal cancer progression by phosphorylating c-MYC at S452, leading to an upregulation of c-MYC expression." (PMID 38622518, 2024). "To further affirm the biological function of STK16 in colorectal cancer proliferation and metastasis, we employed the Crisp-cas9 system to knock out STK16 in RKO and Lovo cancer cells." (PMID 38622518, 2024). "Here, we had demonstrated for the first time that STK16 functioned as an oncogene in colorectal cancer." (PMID 38622518, 2024). "We confirmed that STK16 positively regulated the proliferation, migration, and invasion abilities of colorectal cancer cells." (PMID 38622518, 2024). "The results revealed a significant overexpression of STK16 in colorectal cancer compared to normal colorectal tissues." (PMID 38622518, 2024). "We then examined the expression levels of c-MYC and its downstream genes (GLUT1 and CDK4) in colorectal cancer cells ectopically expressing STK16 or sgSTK16." (PMID 38622518, 2024). "IHC analysis demonstrated a substantial upregulation of STK16 in colorectal cancer, which was further validated by western blot results." (PMID 38622518, 2024). "In conclusion, our findings suggest that pharmacologically inhibiting STK16 might be an effective therapeutic approach for colorectal cancer." (PMID 38622518, 2024). "CCK8 and BrdU assays were conducted to evaluate whether the overexpression of STK16 affected colorectal cancer cell proliferation." (PMID 38622518, 2024). "STK16 plays a positive regulatory role in the progression of colorectal cancer." (PMID 38622518, 2024). "Besides, the proliferation of colorectal cancer mediated by STK16 depended on the phosphorylation of c-MYC at S452." (PMID 38622518, 2024). "Overall, these results suggest that STK16 may function as an oncogene in the progression of colorectal cancer." (PMID 38622518, 2024). "Furthermore, we revealed that STK16 promoted colorectal cancer progression dependent on c-MYC S452 phosphorylation." (PMID 38622518, 2024). "In the present study, we first revealed the oncogenic role of STK16 in colorectal cancer." (PMID 38622518, 2024). "Furthermore, we had revealed that STK16 knock-out or the pharmacological inhibition of STK16 significantly inhibited colorectal cancer proliferation and c-MYC expression in vivo." (PMID 38622518, 2024). "Furthermore, the researchers demonstrated that STK16 knockout or pharmacological inhibition significantly curtailed colorectal cancer proliferation and c-MYC expression in in vivo animal models." (PMID 38622518, 2024). "We demonstrated that STK16 may function as an oncogene in colorectal cancer, positively correlating with cancer cell proliferation and metastasis." (PMID 38622518, 2024). "Additionally, we provided a detailed explanation of the intrinsic mechanisms by which STK16 mediated colorectal cancer progression." (PMID 38622518, 2024). "Importantly, colorectal cancer proliferation mediated by STK16 was found to be dependent on the phosphorylation of c-MYC at S452." (PMID 38622518, 2024). "We first revealed the oncogenic function of STK16 in colorectal cancer." (PMID 38622518, 2024).
colorectal cancer (continued). "Moreover, IHC assays in colorectal cancer tissues demonstrated a positive correlation between STK16 and c-MYC expression levels." (PMID 38622518, 2024). "To further investigate the relationship between STK16 and c-MYC, we generated four types of colorectal cancer cells stably expressing vector + shnc, STK16 + shnc, STK16 + shc-MYC#1, STK16 + shc-MYC#2 using lentivirus." (PMID 38622518, 2024). "Furthermore, we generated four types of colorectal cancer cells stably expressing vector + c-MYC WT, STK16 + c-MYC WT, vector + c-MYC S452A, and STK16 + c-MYC S452A using lentivirus and the Crispr-Cas9 system." (PMID 38622518, 2024). "Additionally, there was no research available on the role of STK16 in colorectal cancer." (PMID 38622518, 2024).
fibrosarcoma (1 paper, 2024). A malignant mesenchymal fibroblastic neoplasm affecting the soft tissue and bone. "Only two studies had revealed that STK16 positively regulated the proliferation ability of lung cancer and fibrosarcoma, with the detailed mechanism by which STK16 regulates tumor growth not thoroughly explored." (PMID 38622518, 2024).
rectal cancer (1 paper, 2024). A primary or metastatic malignant neoplasm that affects the rectum. "GSEA analysis for TCGA database indicated that STK16 positively activated the MYC signaling pathway in both colon and rectal cancers." (PMID 38622518, 2024).
retinal degeneration (1 paper, 2011). Degeneration of the retina. "Our bioinformatics analyses suggest that Env7p is a putative kinase with 29% identity with the human serine/threonine kinase STK16, and Env9p is a putative oxidoreductase with 40% identity with the human retinol dehydrogenase RDH12, a gene associated with retinal degeneration." (PMID 21912603, 2011).
tumor (4 papers, 2022 to 2024). "The results indicated that STK16-IN-1 application not only significantly inhibited the growth and weight of the tumor but also prolonged the overall survival time of mice." (PMID 38622518, 2024). "Serine/threonine kinase 16 (STK16) promotes tumor cell viability and hinders apoptosis through the AKT1 signaling pathway." (PMID 39896803, 2024). "Serine/threonine protein kinase 16 (STK16) plays a critical role in regulating tumor cell proliferation, apoptosis, and prognosis." (PMID 39273000, 2024).
cancer (3 papers, 2019 to 2024). A tumor composed of atypical neoplastic, often pleomorphic cells that invade other tissues. "The results demonstrated that loss of STK16 significantly inhibited the growth rate of cancer cells." (PMID 38622518, 2024). "Immunohistochemistry and western blot assays were performed to assess the expression levels of c-MYC and Ki-67 (representing the proliferation ability of cancer cells), showing that loss of STK16 significantly restrained the expression levels of c-MYC and Ki-67 in vivo." (PMID 38622518, 2024). "Colony formation assays revealed that cancer cells with stable ectopic expression of STK16 displayed a more robust ability for colony formation." (PMID 38622518, 2024). "In summary, these findings confirm that the overexpression of STK16 significantly enhances the proliferation and metastatic capabilities of cancer cells." (PMID 38622518, 2024). "STK16 inhibition, either genetically or pharmacologically, effectively curtails cancer growth and c-MYC expression in vivo." (PMID 38622518, 2024). "The results demonstrated overexpression of STK16, and patients with higher STK16 expression levels had worse clinical prognoses in most types of cancer." (PMID 38622518, 2024). "The results indicated that the gain of STK16 enhanced the proliferation ability of cancer cells, while c-MYC silencing counteracted this effect." (PMID 38622518, 2024). "STK16 had garnered attention in recent researches, while its involvement in cancer had been minimally explored." (PMID 38622518, 2024). "In summary, these results provide evidence that STK16 plays a positive regulatory role in cancer cell proliferation and metastasis." (PMID 38622518, 2024). "Moreover, we demonstrated that STK16 knock-out markedly suppressed the colony formation, migration, and invasion abilities of cancer cells." (PMID 38622518, 2024). "STK16-IN-1 could reduce cancer cell numbers and potentiate the antiproliferative effects of some chemotherapeutics." (PMID 30974739, 2019). "Additionally, the role of STK16 in other types of cancers was explored." (PMID 38622518, 2024). "However, limited research had been conducted on the role of STK16 in cancer." (PMID 38622518, 2024). "Thus, inhibition of STK16 is expected to be developed as a novel therapeutic approach for cancers." (PMID 30974739, 2019). "We also confirmed that the STK16 inhibitor significantly suppressed c-MYC expression and the proliferation ability of cancer cells in both in vitro and in vivo experiments." (PMID 38622518, 2024). "Consistently, STK16 overexpression enhanced the proliferation ability of cancer cells in c-MYC WT cancer cells, but not in c-MYC S452A cancer cells." (PMID 38622518, 2024). "Results showed that STK16 overexpression upregulated the expression levels of c-MYC, GLUT1, and CDK4 in c-MYC WT cancer cells, but not in c-MYC S452A cancer cells." (PMID 38622518, 2024).
STK16 also shares sentences with these, for which no sentence is quoted: infection (7 papers); glioma (1); iron deficiency (1); lung carcinoma (1); porphyria (1); virus infection (1).